SNORA50D (small nucleolar RNA, H/ACA box 50D)
Gene: Small nucleolar RNA gene on chromosome 5 (69,160,808 to 69,160,939, forward strand). Ensembl gene ENSG00000280894.
Gene Ontology:
Biological process: RNA processing
Cellular component: nucleolus
Homologues: Orthologues: chimpanzee SNORA50D (98% identical), macaque SNORA50D (82% identical). Paralogues in human: SNORA50C (80% identical), SNORA50B (60% identical), SNORA50A (54% identical).